ODAD2 (outer dynein arm docking complex subunit 2)
Description:
Component of the outer dynein arm-docking complex (ODA-DC) that mediates outer dynein arms (ODA) binding onto the doublet microtubule. Involved in mediating assembly of both ODAs and their axonemal docking complex onto ciliary microtubules.
Synonyms: ARMC4; FLJ10817; FLJ10376; DKFZP434P1735; CILD23; gudu
Tractability: Small molecule: a structure with a bound ligand is known. PROTAC: ubiquitination databases record sites on it.
Gene: Protein-coding gene on chromosome 10 (27,775,186 to 27,999,532, reverse strand). Ensembl gene ENSG00000169126.
Subcellular location: Cytoplasm, cytoskeleton, cilium axoneme; Cytoplasm, cytoskeleton, cilium basal body
Subcellular location (Human Protein Atlas): End piece; Acrosome; Principal piece
Gene Ontology:
Molecular function: protein binding
Biological process: cilium movement; determination of left/right symmetry; outer dynein arm assembly; regulation of cilium beat frequency; flagellated sperm motility
Cellular component: axoneme; ciliary base; cilium
Genetic constraint (gnomAD): Loss-of-function variants: 66 observed, 82.89 expected, observed/expected ratio (o/e) 0.8, 90% interval 0.65 to 0.98. The upper end of that interval is the gene's LOEUF score, 0.98, which puts it in group 4 of 6, group 1 being the genes least tolerant of losing a copy. Missense variants: 1,039 observed, 1,122 expected, observed/expected ratio (o/e) 0.93, 90% interval 0.88 to 0.98. Synonymous variants: 368 observed, 402.37 expected, observed/expected ratio (o/e) 0.91, 90% interval 0.84 to 1.
Gene-disease validity (ClinGen):
ClinGen rates the evidence that ODAD2 causes each of these diseases.
primary ciliary dyskinesia 23 (autosomal recessive): Definitive.
Homologues: Orthologues: macaque ODAD2 (96% identical), chimpanzee ODAD2 (94% identical), pig ODAD2 (87% identical), mouse Odad2 (85% identical), guinea pig ODAD2 (85% identical), rat Odad2 (84% identical), tropical clawed frog odad2 (68% identical), zebrafish odad2 (58% identical), Drosophila melanogaster gudu (27% identical). Paralogues in human: ANKAR (14% identical), ARMC3 (13% identical), JUP (12% identical), CTNNB1 (11% identical).
Diseases named in the same sentence as ODAD2 in open-access papers:
ODAD2 is named in the same sentence as 36 diseases in open-access papers, as found by Europe PMC text mining. Sharing a sentence is not in itself a finding about the gene and the disease. The quoted sentences say what the papers report.
primary ciliary dyskinesia (15 papers, 2015 to 2026). A rare, genetically heterogeneous, primarily respiratory disorder characterized by chronic upper and lower respiratory tract disease. "Whole-exome sequencing excluded known monogenic IEIs, autoinflammatory, or hereditary amyloidosis genes; a heterozygous likely pathogenic variant in ODAD2 (associated with primary ciliary dyskinesia) was considered incidental." (PMID 42278892, 2026). "Genetic variants of outer dynein arm docking complex subunit 2 (ODAD2) have been reported to be closely associated with primary ciliary dyskinesia and colorectal cancer in previous studies, but the association of genetic variants of ODAD2 with hepatocellular carcinoma (HCC) has not been reported." (PMID 37833735, 2023). "Through a literature search, we also observed that the ODAD2 gene is markedly related to primary ciliary dyskinesia (PCD) and colorectal cancer (CRC)." (PMID 37833735, 2023).
liver cancer (1 paper, 2023). An epithelial or non-epithelial malignant neoplasm that arises from the liver. "After screening in the previous preliminary research, we initially identified that outer dynein arm docking complex subunit 2 (ODAD2)-rs7893462 may be associated with the occurrence and prognosis of liver cancer." (PMID 37833735, 2023).
tumor (4 papers, 2022 to 2024). "At the same time, the detection of clinical tissue expression showed that ODAD2 was significantly downregulated in tumor tissues, which may play a tumor suppressor role in CRC." (PMID 37833735, 2023). "Importantly, the lower ODAD2 expression in patient tumors than normal tissues indicate its potential tumor suppressor function in CRC." (PMID 38203325, 2023). "We showed that a high expression of ODAD2 downregulated the expression of NF-κB-dependent genes, dramatically reduced NF-κB activity, cellular proliferation, anchorage-independent growth, and migratory ability in vitro, and significantly decreased xenograft tumor growth in vivo." (PMID 38203325, 2023).
ODAD2 also shares sentences with these, for which no sentence is quoted: male infertility (4 papers); cancer (3); ciliopathies (2); colorectal cancer (2); gastric cancer (2); sarcoma (2); asthma (1); breast carcinoma (1); bronchiectasis (1); chronic gastritis (1); chronic rhinosinusitis (1); deafness (1); heart malformations (1); hepatocellular carcinoma (1); hereditary amyloidosis (1); infection (1); infertile (1); Joubert syndrome (1); Kartagener Syndrome (1); melanoma (1); metastatic cancer (1); nasopharyngeal carcinoma (1); nervous system disorder (1); ovarian carcinoma (1); paranasal sinus diseases (1); Recurrent otitis media (1); Recurrent respiratory infections (1); recurrent sinus disease (1); Respiratory insufficiency (1); Respiratory tract infection (1).
A further 3 diseases each share a sentence with ODAD2 in 1 paper.